MTOR (mechanistic target of rapamycin kinase)
Diseases named in the same sentence as MTOR in open-access papers (continued):
Sharing a sentence is not in itself a finding about the gene and the disease.
prostate carcinoma (continued). "However, silencing of mTOR enhanced the sensitivity of PC-3 cells to the growth-inhibitory effects of bardoxolone methyl, suggesting that Akt and mTOR are key molecular targets of bardoxolone methyl in prostate cancer cells." (PMID 40732256, 2025). "Hyper-activation of this pathway, often driven by loss of the tumor suppressor phosphatase and tensin homolog (PTEN) or AKT and mTOR dysregulation, facilitates the transition to castration-resistant prostate cancer by compensating for suppression of androgen receptor signaling." (PMID 41375042, 2025). "The PI3K/AKT/mTOR signaling pathway directly related to the cell growth, proliferation and apoptosis of prostate cancer cells could also be modulated by cap-independent translation of the mTOR transcript." (PMID 39936974, 2025). "PI3K/AKT/mTOR signaling is frequently upregulated in prostate cancer." (PMID 40427108, 2025). "Furthermore, we showed that rapamycin-treated SESN2-overexpressed cells further increased the protein level of p-AMPK and further decreased mTOR in prostate cancer cells." (PMID 40661871, 2025). "Furthermore, in the context of prostate cancer, the inhibition of mTOR signalling exhibited remarkable efficacy in suppressing tumour growth and attenuating the activity of associated downstream signalling pathways." (PMID 40429821, 2025). "Moreover, the GLP-1 analogue exendin 4 inhibits the growth of prostate cancer cells through suppressing PI3K/Akt/mTOR signaling pathway." (PMID 40361502, 2025). "From the perspective of signaling pathways, mainstream research indicates that glutamine addiction is associated with the progression and metastasis of prostate cancer cells through three distinct pathways: the AR pathway, the MYC pathway, and the PTEN/PI3K/mTOR pathway." (PMID 41179661, 2025). "Therefore, western blotting was used to determine how DDIT4 affects the PI3K-Akt-mTOR signaling pathway during prostate cancer EMT." (PMID 38384328, 2024). "As evidence of this, a key regulator of lipid homeostasis, SREBPs (Sterol Regulatory Element-Binding Proteins), and a crucial sensor for nutrient signaling, the mammalian target of rapamycin (mTOR), have been reported to influence lipogenesis to drive prostate cancer growth and progression." (PMID 38097734, 2024). "However, the DHA component of PZ-DHA inhibits the phosphorylation of Akt at ser473 and thr308, as well as mTOR phosphorylation, in human prostate cancer cells." (PMID 39062483, 2024). "Our findings show that CA is able to inhibit both Akt and mTOR and have effects similar to clinically evaluated inhibitors of these pathways, providing strong rationale for continuing the examination of the effects of CA in prostate cancer." (PMID 38732504, 2024). "Collectively, these findings established gnetin C as a new natural compound with anticancer properties against MTA1/AKT/mTOR-activated prostate cancer, with potential as monotherapy and as a possible adjunct to clinically approved mTOR pathway inhibitors in the future." (PMID 38611022, 2024). "In prostate cancer, overexpression of miR-34a upregulates the phosphorylation of mTOR." (PMID 39201363, 2024). "Therefore, in the future, combinatorial targeted therapies can be beneficial to a biomarker-selected subpopulation of patients with MTA1/mTOR activation-mediated advanced prostate cancer." (PMID 38611022, 2024). "Similarly, in vitro experiments, Piezo1 downregulation induced reduced migration of prostate cancer cells by inhibiting Akt and mTOR phosphorylation." (PMID 38690080, 2024). "On the other hand, the Akt kinase of the PI3K/AKT/mTOR pathway is associated with platelet activation, which, together with mutations in PI3K enzymes, may explain both metastasis and thrombosis in prostate cancer." (PMID 39337387, 2024). "Dysregulation of the mTOR pathway is frequently observed in cancer, including prostate cancer." (PMID 39125671, 2024).
prostate carcinoma (continued). "Existing ambiguity surrounding the biological role of p-mTOR/mTOR in prostate cancer could explain the limited clinical efficacy of PI3K/AKT/mTOR inhibitors." (PMID 38611022, 2024). "Importantly, NPRL2 overexpression was shown to promote proliferation and docetaxel chemoresistance of prostate cancer cells through a mechanism that involves inhibition of the mTOR pathway." (PMID 38915098, 2024). "In PC-3 prostate cancer cells mTOR and p70 S6K was inhibited with RE and carnosol (COH) treatment." (PMID 38732504, 2024). "To gain initial insights regarding the mechanistic basis for targeting the MTA1/mTOR pathway, we first investigated the link between MTA1 and mTOR signaling in PC3M prostate cancer cells, which are known to have a PTEN-null status and the highest MTA1 expression of all prostate cancer cell lines." (PMID 38611022, 2024). "Hence, suppression of the mTOR signaling pathway improves radiosensitivity in radioresistant prostate cancer cells by suppressing colony formation, increasing apoptosis, and decreasing autophagy." (PMID 38965615, 2024). "Similarly, RPL22L1 has the capability to activate the PI3K/Akt/mTOR pathway, promoting the proliferation of prostate cancer cells, offering a promising avenue for prostate cancer therapy." (PMID 39684863, 2024). "In prostate cancer, mTOR downregulates the expression of glycogen synthase kinase 3 (GSK-3)." (PMID 39349424, 2024). "In 50% of prostate cancer, the PI3K/Akt/mTOR is seen to be upregulated due to the loss of PTEN." (PMID 37214073, 2023). "LATs promote the progression of prostate cancer by increasing amino acid uptake, activating the mammalian target of rapamycin (mTOR) pathway and downstream signals, mediating castration-resistance, promoting tumor angiogenesis, and enhancing chemotherapy resistance." (PMID 37047148, 2023). "mTORC1 stimulates transcription and translation and contains several proteins, including the regulatory-associated protein of mTOR (RAPTOR) and the DEP domain-containing mTOR-interacting protein (DEPTOR), which is often overexpressed in late-stage prostate cancer." (PMID 36768610, 2023). "Moreover, an increase in the mTOR level in the nucleus is correlated with poor prognosis in prostate cancer patients." (PMID 37176048, 2023). "The direct interaction between SLFN5 and ATF4 in prostate cancer results in mTOR activation." (PMID 36900220, 2023). "AR signaling also impacts the cellular metabolism reprogramming observed in prostate cancer via binding, together with mTOR, to regulatory regions of the sterol regulatory element-binding transcription factor 1 (SREBF1) gene, which leads to increased expression." (PMID 36768610, 2023). "The PI3K/Akt/mTOR pathway plays a prominent role in prostate cancer." (PMID 37214073, 2023). "Interestingly, the concept of combined anti-mTOR and anti-endocrine therapy also demonstrated promising results in prostate cancer." (PMID 37623437, 2023). "In particular, the results of this study indicate that variations in phosphatidylserine exposure, membrane permeabilization, and cellular apoptosis by wt-ANXA7 and DNTM variant were associated with differential IP3 receptor expression and PI3K/AKT/mTOR modulation in prostate cancer cells." (PMID 37240163, 2023). "Similar to HDAC inhibition, targeting the PI3K/AKT/mTOR pathway alone may be insufficient to halt prostate cancer progression and combination approaches are likely necessary." (PMID 37823778, 2023). "Interestingly, ectopic overexpression of SphK1 and SphK2 further increased Akt-mTOR activation in primary prostate cancer cells." (PMID 37604912, 2023). "Considering that activation of Akt is vital for the progression of prostate cancer, we examined whether SKI-178 could inhibit activation of Akt and its major downstream mTOR in prostate cancer cells." (PMID 37604912, 2023).
prostate carcinoma (continued). "A proteomic profiling of the mTOR complex bound to chromatin in different prostate cancer cell lines shows the androgen-dependent binding of the AR and the additional important function of the nucleosome remodeling deacetylase NuRD complex for the regulation of gene expression." (PMID 36768610, 2023). "PI3K/AKT/mTOR signaling plays an essential role in prostate cancer and in resistance to therapies." (PMID 36768610, 2023). "Thus, auraptene-induced AMPK activation apparently suppresses the cell growth of prostate cancer cells via at least three mechanisms, i.e., by inhibiting lipid metabolism, AR, and the mTOR/S6 kinase pathway." (PMID 37958994, 2023). "The antitumor effects of metformin on breast and prostate cancer cells have been demonstrated in in vivo and in vitro experiments, since rapamycin/ribosomal protein S6 kinase beta-1 (mTOR/S6K1) activity is suppressed by adenosine monophosphate-activated protein kinase (AMPK) activation." (PMID 36837499, 2023). "The expression of mTOR was positively correlated with tumor malignancy in prostate cancer subjects." (PMID 35082928, 2022). "Similarly, numerous studies have shown that TXNIP inhibits mTOR signaling in prostate cancer and that mTOR signaling inhibition induces TXNIP expression." (PMID 36366411, 2022). "GNE-493 blocked Akt-mTOR activation in primary human prostate cancer cells." (PMID 35296639, 2022). "Therefore, a large number of studies are still needed to further clarify the effect of Tanshinone on the mTOR-mediated signaling pathway in prostate cancer cells." (PMID 36080361, 2022). "In GNE-493-treated prostate cancer xenografts, Akt-mTOR inactivation was also detected." (PMID 35296639, 2022). "GNE-493 blocked Akt-mTOR activation in prostate cancer cells." (PMID 35296639, 2022). "Mutations in the PI3K/Akt/mTOR (mechanistic target of rapamycin kinase)-pathway are amongst the most common across different types of cancer, including not only CRC but also lung, breast, and prostate cancer, which have collectively killed more than three million people worldwide in 2020." (PMID 35780223, 2022). "The PI3K/Akt/mTOR pathway is well known to be hyperactive in prostate cancer." (PMID 35216092, 2022). "Results suggested that following the PI3K/Akt/mTOR signaling pathway, tangeretin effectively induced reprogramming of epithelial to mesenchymal transition and the expression level of mesenchymal proteins in prostate cancer cells was reduced." (PMID 35795855, 2022). "Curcumol may also alter the development of prostate cancer via regulating the PDK1/AKT/mTOR signaling pathway via miR-9." (PMID 35889217, 2022). "Also, as a tumor suppressor miRNA, miR-100-5p can inhibit the proliferation, migration, and invasion of prostate cancer cells by downregulating the expression of mTOR." (PMID 35465266, 2022). "The expression of mTOR is positively correlated with tumor malignancy in prostate cancer." (PMID 35082928, 2022). "Concerted targeting of integrin subtypes along with Akt-mTOR signaling could, therefore, open options to prevent progressive dissemination of prostate cancer." (PMID 35053528, 2022). "PI3K-Akt-mTOR inhibitors have yielded promising anti-prostate cancer results." (PMID 35296639, 2022). "miR-139 mediates Akt/mTOR pathway inhibition and enhances autophagy in prostate cancer cells." (PMID 35309939, 2022). "This suggests that the combined inhibition of mGluR1 alongside PI3K/mTOR could potentially be of benefit for patients with PTEN wild-type prostate cancer." (PMID 35086953, 2022). "In vivo studies on synthetic PI3K/Akt/mTOR inhibitors in prostate cancer." (PMID 34452154, 2021). "In vivo studies on natural PI3K/Akt/mTOR inhibitors in prostate cancer." (PMID 34452154, 2021). "The crosstalk between the PIK3 and mTOR pathways can promote prostate cancer progression." (PMID 34316327, 2021). "XHP can suppress the proliferation of prostate cancer via inhibitions of the PI3K/Akt/mTOR pathway." (PMID 35342388, 2021).
prostate carcinoma (continued). "Initial attempts to inhibit this signalling pathway in prostate cancer-targeted mTOR protein." (PMID 35011901, 2021). "Related studies have found that GLP-1RAs could limit the growth of prostate cancer by inhibiting the PI3K/AKT/mTOR and ERK/MAPK pathways, while could also limit the growth of pancreatic and prostate cancer cells by inhibiting the NF-kB pathway." (PMID 34497589, 2021). "In prostate cancer, the deregulation of the PI3K-Akt-mTOR pathway may be mainly driven by PTEN loss of function." (PMID 35011901, 2021). "In addition, a key role for the PI3K/AKT/mTOR signaling cascade in the development of castrate resistant prostate cancer (CRPC) has been previously proposed." (PMID 34682865, 2021). "Given the role of PI3K and mTOR in the response of prostate cancer cells to radiation and hypoxia, preclinical studies investigated whether PI3K/AKT/mTOR inhibitors radiosensitized prostate cancer cells of different PTEN status." (PMID 35004302, 2021). "Additionally, resveratrol evokes autophagic cell death in a stromal interaction molecule 1 (SIMI)-dependent way, while involving the downregulation of mTOR pathway in human prostate cancer cells PC3 and DU145." (PMID 34512368, 2021). "In LNCaP prostate cancer cells, Staufen1 regulates cell proliferation through mTOR activation." (PMID 33541283, 2021). "Current standard of care includes diverse treatment modalities such as hormonal therapy in prostate cancer, chemotherapy for urothelial and testicular cancer and targeted treatment of vascular–endothelial growth factor and mammalian target of rapamycin (mTOR) signaling in RCC." (PMID 34771578, 2021). "Mechanistic evaluation in prostate cancer cell line models suggests that AR-mediated regulation of the pentose phosphate pathway occurs through upregulation of G6PD in response to mTOR,52 resulting in the production of nucleotide precursors for DNA synthesis and NADPH to sustain lipogenesis." (PMID 34262149, 2021). "Moreover, tangeretin inhibits EMT in PC-3 prostate cancer cells by downregulating the PI3K/Akt/mTOR pathway." (PMID 34335799, 2021). "Related studies have found that GLP-1RAs can inhibit the PI3K/AKT/mTOR and ERK/MAPK pathways, thereby inhibiting the growth of prostate cancer; however, whether GLP-1RAs increase the risk of pancreatitis remains controversial." (PMID 34497589, 2021). "A reciprocal regulatory connection has also been observed between ASCT2, LAT1 and mTOR in prostate cancer, hepatoma, lymphoma and leukemic cells, since glutamine starvation-induced LAT1-mediated transport of amino acids or expression and/or leucine deprivation induced the same effects on ASCT2." (PMID 33429909, 2021). "Clinical studies on PI3K/Akt/mTOR inhibitors in prostate cancer." (PMID 34452154, 2021). "Deregulation of the PI3K/Akt/mTOR pathway in cancer has been well-established and different clinical studies have found an overactivation of this pathway in ~40% of breast cancers and 50% of primary prostate cancers." (PMID 32656088, 2020). "PIM and PI3K/mTOR pathways are often dysregulated in prostate cancer, and may lead to decreased survival, increased metastasis and invasion." (PMID 32873828, 2020). "In addition, inhibition of mTOR pathway enhanced radiosensitivity in radioresistant prostate cancer cells via repressing colony formation, inducing more apoptosis, and reducing autophagy." (PMID 33336000, 2020). "A novel proteasome inhibitor marchantin M could directly trigger autophagic cell death via PI3K/AKT/mTOR pathway in prostate cancer cells." (PMID 33239065, 2020). "Oncogenic activation of the phosphatidylinositol-3-kinase (PI3K), protein kinase B (PKB/AKT), and mammalian target of rapamycin (mTOR) pathway is a frequent event in prostate cancer that facilitates tumor formation, disease progression and therapeutic resistance." (PMID 32630372, 2020).
prostate carcinoma (continued). "Also, Salinomycin, a natural compound isolated from Streptomyces albus, was shown to induce p38 MAPK-mediated downregulation of the AKT/mTOR pathway, protective autophagy, and apoptosis in human prostate cancer cells." (PMID 32155920, 2020). "miR-146b inhibited autophagy in prostate cancer by targeting the PTEN/Akt/mTOR signaling pathway, and it may be a potential target for prostate cancer." (PMID 32051823, 2020). "The expression level of mTOR was significantly up-regulated in patients with prostate cancer." (PMID 33335853, 2020). "Moreover, a study by Fan explored the function of PRRT3-AS1 in prostate cancer and reported that PRRT3-AS1 silencing inhibited the invasion, migration, and proliferation of prostate cancer cells through the mTOR signaling pathway." (PMID 33101369, 2020). "Strengthening these findings, more recently, the activation of mTOR was able to enrich the pool of CSCs within DCCs in bone marrow (BM) metastatic niches in prostate cancer models, through a mechanism involving the release of growth arrest specific 6 (GAS6) by osteoblasts." (PMID 33193295, 2020). "Thus, DEPTOR inhibits prostate tumorigenesis by inactivating mTOR signals, suggesting the potential use of mTOR inhibitors to treat prostate cancer with low DEPTOR expression." (PMID 31685947, 2020). "Interestingly, in castration-resistant prostate cancer cells, MTOR transcriptional activity and modulation of metabolic programs occurred even in the absence of androgens." (PMID 30072418, 2019). "In addition to the previously discussed roles of MTOR in regulating translation, it has emerged that MTOR can directly influence the transcription of metabolic genes of prostate cancer cells via its interaction with androgen receptor in the nucleus." (PMID 30072418, 2019). "The mTOR pathway is reported to be significantly active in prostate cancer." (PMID 30754640, 2019). "In addition, PI3K and mTOR are essential regulators of radiation resistance in prostate cancer cells as dual PI3K-mTOR inhibitors re-sensitize cancer cells to radiation treatment." (PMID 31288154, 2019). "Since VPA administration reversed acquired resistance towards temsirolimus in prostate cancer cells, combined application of an mTOR and HDAC inhibitor may be a novel concept in treating CRPC patients." (PMID 31010254, 2019). "To better understand the genetic and biological regulatory mechanisms of prostate cancer, we conducted a meta-analysis of three major pathways i.e. androgen receptor (AR), mechanistic target of rapamycin (mTOR) and Mitogen-Activated Protein Kinase (MAPK) on prostate cancer." (PMID 31136301, 2019). "However, the clinical trial of mTOR inhibitor in men with castrate-resistant prostate cancer has been disappointing with few responses and a short time to progression." (PMID 29963230, 2018). "Notably, they included DMRs close to many genes previously implicated in prostate cancer (e.g., NEAT1, MTOR, RHCG, KCNC2, WT1, HOXC12, KMT2B)." (PMID 30318509, 2018). "Notably, Sal decreases the phosphorylation of AKT and the phosphorylation of mTOR in prostate cancer cells." (PMID 29433536, 2018). "This corroborates other studies that suggest Tan IIA may inhibit PI3K/Akt/mTOR signaling in gastric carcinoma and prostate cancer models, and serves as a validation for the efficacy and accuracy of our chemogenomics-based strategy." (PMID 29416003, 2018). "PI3K/Akt/mTOR/p70S6K signaling pathway is a commonly activated pathway in prostate cancer cells." (PMID 30555320, 2018). "This study was designed to investigate whether epigenetic modulation by histone deacetylase (HDAC) inhibition might circumvent resistance towards the mechanistic target of rapamycin (mTOR) inhibitor temsirolimus in a prostate cancer cell model." (PMID 30200497, 2018).